METTL3 (methyltransferase 3, N6-adenosine-methyltransferase complex catalytic subunit)
Diseases named in the same sentence as METTL3 in open-access papers (continued):
Sharing a sentence is not in itself a finding about the gene and the disease.
liver fibrosis (17 papers, 2021 to 2026). "Liver fibrosis patients and animal models had considerably higher levels of ASIC1a expression, and METTL3 was linked to ASIC1a’s promotion of liver fibrosis." (PMID 37020540, 2023). "Mechanistically, METTL3 was associated with ASIC1a promoting liver fibrosis and subsequently regulated the DGCR8-mediated synthesis of miR-350 by m6A modification." (PMID 37227534, 2023). "Concomitantly, we observed the increase of both MALAT1 and METTL3 in these cells, suggesting that the up-regulations of MALAT1 and METTL3 in macrophages were closely associated with the development of liver fibrosis." (PMID 34839365, 2021). "A preprint reported that METTL3 promoted the progression of hepatic fibrosis through YTHDF2-mediated silencing of GPR161 in a m6A-dependent manner." (PMID 40100806, 2025). "Another study showed that acid-sensitive ion channel 1a (ASIC1a) promoted liver fibrosis by regulating miR-350 through METTL3-dependent m6A modification." (PMID 37020540, 2023). "To see the integrated effect of different stimulation on Mettl3 cKO B cells, we used the CCl4-induced liver fibrosis model, in which Mettl3 in B cells was upregulated." (PMID 35747688, 2022). "Using Mettl3flox/flox/Alb-Cre mice, we found that Mettl3 cKO mice got steatosis at about 2 weeks after birth, liver fibrosis at 4–5 weeks, and finally died before 7 weeks due to severe liver injury." (PMID 35931692, 2022). "Given the published dataset, we found that Mettl3 was upregulated in B cells of fibrotic livers, indicating that Mettl3 was involved in B cell function in liver fibrosis." (PMID 35747688, 2022). "Our study demonstrated that Mettl3 marginally affects Cd19+ B cell development, activation, and profibrogenic function in liver fibrosis." (PMID 35747688, 2022). "As B cell contributes to hepatic fibrosis in an antibody-independent way, and Mettl3 was increased in B cells from fibrotic livers in published datasets, we explored the function of Mettl3 on B cells invivoby using CCl4-induced liver fibrosis model." (PMID 35747688, 2022). "In KCs isolated from in vivo liver fibrosis model or in vitro M1-polarized macrophages, METTL3 was up-regulated, and sequentially, it increased MALAT1 level via m6A methylation, which promoted USP8 mRNA degradation through the interaction with PTBP1." (PMID 34839365, 2021). "In conclusion, here we showed that the METTL3/MALAT1/PTBP1/USP8/TAK1 axis was activated in macrophages during the development of liver fibrosis." (PMID 34839365, 2021). "MALAT1 and METTL3 expressions presented a time-dependent increase with the progression of CCL4-induced liver fibrosis." (PMID 34839365, 2021). "To understand the interaction between MALAT1 and METTL3 within macrophages during liver fibrosis, we first established an in vivo CCl4-induced liver fibrosis model." (PMID 34839365, 2021). "Additionally, as mentioned in the pulmonary fibrosis section, the maturation of miRNA regulated by METTL3-mediated m6A modification was also found to be involved in hepatic fibrosis." (PMID 39756462, 2025). "Accumulating evidence has shown that m6A-related enzymes regulate liver fibrosis; for example, Chaiet al. revealed that Mettl3 deficiency attenuated HSC activation and CCl4-induced liver fibrosis, and Liuet al. reported that the m6A reader YTHDF3 alleviated CCl4-induced liver fibrosis." (PMID 39175431, 2024). "Likewise, in liver fibrosis models, METTL3 and MALAT1 were upregulated in Kupffer cells and macrophages cells." (PMID 37227534, 2023). "In summary, our study demonstrated that deletion of Mettl3 from the pro-B stage on has minimal effects on B cell development and function, as well as profibrogenic activity of B cells in liver fibrosis, revealing a stage-specific dependence on Mettl3-mediated m6A of B cell development." (PMID 35747688, 2022).
liver fibrosis (continued). "To identify whether Mettl3 regulates B cell function in vivo, we subjected WT and Mettl3 cKO mice to CCl4-induced liver fibrosis, a well-established and widely-used hepatotoxic fibrosis model." (PMID 35747688, 2022). "Considering that the development of liver fibrosis involves multiple cell types in addition to macrophages, future studies should extend to other cell types and explore the importance and mechanisms of METTL3 in each cell type as well as in liver as a whole." (PMID 34839365, 2021). "To address whether the increased steatohepatitis in Mettl3-HKO mice also promotes liver fibrosis and immune cell infiltration, we measured pathological collagen deposition and immune cell infiltration using Sirius Red staining and F4/80 immunostaining, respectively." (PMID 34893641, 2021). "Activation of METTL3 and METTL14 amplifies TGF-β1 mRNA levels in an m6A-dependent manner, further emphasizing the involvement of m6A modifications in hepatic fibrosis." (PMID 39756462, 2025). "Knockdown of METTL3/METTL14 significantly inhibited macrophage activation and secretion and slowed the progression of liver fibrosis." (PMID 38902779, 2024). "The METTL3/MALAT1/PTBP1/USP8/TAK1 axis stimulated pyroptosis and inflammation of macrophages, leading to the aggravation of liver fibrosis." (PMID 37227534, 2023). "The activation of HSCs is a key process of liver fibrosis, and HSC-specific knockout of METTL3 inhibits HSC activation and significantly alleviates liver fibrosis." (PMID 37227534, 2023). "First, we detected the progressive up-regulations of METTL3 and MALAT1 in KCs from in vivo CCl4-induced liver fibrosis and from in vitro M1-polarized macrophages." (PMID 34839365, 2021). "The signaling cascade METTL3/MALAT1/PTBP1/USP8/TAK1, by essentially stimulating pyroptosis and inflammation of macrophages, aggravates liver fibrosis." (PMID 34839365, 2021). "In this study, we reported not only the relevance of METTL3 (a protein, when dimerized with METTL14, responsible for m6A methylation of RNA molecules) to the pathogenesis of liver fibrosis, but its essential role in controlling the stability of lncRNA MALAT1." (PMID 34839365, 2021). "METTL3 inhibition, achieved via genetic knockdown or selective inhibitors, affects HSC activation and fibrotic gene expression, supporting its role as a therapeutic target in AFB1-induced liver fibrosis." (PMID 42204714, 2026). "Notably, pharmacological activation of Mettl3 in adult hepatocytes substantially mitigated PSC progression and liver fibrosis." (PMID 41431138, 2025). "In a study using HSC-specific Mettl3 knockout mice, the expression of pro-fibrotic genes, including Acta2, Col1a1, and Timp1 were decreased with Mettl3 inhibition, suggesting a HSC-specific role for m6A in liver fibrosis." (PMID 37628704, 2023). "In addition, the METTL3/MALAT1/PTBP1/USP8/TAK1 axis in liver fibrosis promotes pyroptosis and macrophage M1 polarization, thereby exacerbating liver fibrosis progression." (PMID 37063421, 2023). "We observed that Cd19-Cre-mediated Mettl3 deletion does not affect the profibrogenic activity of B cells in CCl4-induced liver fibrosis in vivo." (PMID 35747688, 2022). "Here, we showed that the profibrogenic activity of B cells in liver fibrosis is independent of cell-autonomous Mettl3-mediated m6A modification." (PMID 35747688, 2022). "Furthermore, this targeted reduction of METTL3 does not influence the fibrotropic activity of B cells in the context of liver fibrosis." (PMID 39072324, 2024). "This suggests that while m6A modifications are crucial for B cell development, the specific role of METTL3 knockdown at the pro-B stage might not significantly affect B cell development or function in certain contexts, such as liver fibrosis." (PMID 39072324, 2024). "In contrast, in the liver fibrosis stage of NAFLD, METTL3 may become a promoter of disease." (PMID 37671161, 2023).
liver fibrosis (continued). "In addition, B cell-specific Mettl3 knockout had no influence on the pro-fibrogenic activity of B cells in liver fibrosis, evidenced by comparable fibrosis in carbon tetrachloride- (CCl4-) treated Mettl3 cKO mice and WT controls." (PMID 35747688, 2022). "The results showed that Mettl3 deletion in B cells does not affect liver fibrosis progression." (PMID 35747688, 2022).
diabetic nephropathy (16 papers, 2022 to 2026). "Previous studies have reported that high glucose and AGEs induce METTL3 expression to promotes the progression of diabetic bone loss, diabetic retinopathy, and diabetic nephropathy." (PMID 38982516, 2024). "Another study showed that Mettl3 promotes podocyte injury in diabetic nephropathy via TIMP2 mRNA m6A modification." (PMID 40765834, 2025). "A recent study reported that METTL3 is also increased in podocytes from patients with diabetic nephropathy, as observed in renal biopsy samples." (PMID 40066222, 2025). "METTL3 serves as a dual-function mediator-pro-oncogenic in RCC via HIF-1α-PLOD2 while pro-fibrotic in diabetic nephropathy through TIMP2/Notch-while consistently amplifying TGF-β signaling across AKI/CKD/obstructive nephropathy." (PMID 40895041, 2025). "In podocytes, AGEs increased the expression of METTL3, which promoted podocyte death after DM through pro-inflammatory and pro-apoptotic effects, ultimately exacerbating diabetic nephropathy." (PMID 38982516, 2024). "The M6A modification of TIMP2 mRNA mediated by METTL3 in podocyte injury in diabetic nephropathy not only promotes inflammatory damage, but also apoptosis." (PMID 37865763, 2023). "The METTL3 expression level was notably upregulated in the podocytes of patients with diabetic nephropathy and the kidneys of type 1 and type 2 diabetic mice." (PMID 36457997, 2022). "METTL3 targets TUG1/PGC-1α and ameliorates mitochondrial dysfunction in diabetic nephropathy in an IGF2BP2-dependent manner." (PMID 40685567, 2025). "In the development of diabetic nephropathy, with the assistance of IGF2BP2, METTL3-mediated M6A modification of TIMP2 is involved in inflammatory damage in podocytes by regulating Notch signaling." (PMID 37865763, 2023). "Besides METTL3, METTL14 expression was also found to be upregulated in glomerular endothelial cells cultured with kidney tissue from patients with diabetic nephropathy combined with high glucose levels." (PMID 40066222, 2025). "This study showed that METTL3 in mesangial cells can improve their mRNA stability by promoting NSD2 M6A modification with the participation of YTHDF1, reducing interstitial fibrosis and alleviating the progression of diabetic nephropathy." (PMID 37865763, 2023).
colitis (15 papers, 2017 to 2025). Inflammation of the colon. "The increased expression of METTL3 in macrophages is associated with the development of colitis, and depletion of METTL3 in macrophages can protect mice from colitis induced by dextran sulfate sodium." (PMID 40829428, 2025). "The present study aimed to assess the critical role of UAF1 in colitis, its potential upstream key regulator METTL3, and the underlying mechanisms driving inflammation." (PMID 39966502, 2025). "The in vivo investigations revealed the treatment effects of si‐circPRKAR1B and si‐METTL3 in colitis models of IL‐10‐deficient mice." (PMID 37679886, 2023). "Loss of Mettl3 in IECs or Lgr5+ stem cells suppressed the differentiation and self-renewal of ISCs, especially restricted the early differentiation and maturation of goblet cells in colon, and then induced colitis." (PMID 39762134, 2025). "Besides, our previously work showed that Mettl3 deficiency impaired the differentiation of naive T cells, thereby preventing colitis in a lymphopaenic mouse adoptive transfer model." (PMID 39762134, 2025). "The Mettl3-deficient naïve T-cells were defective in adoptive transfer colitis experiments using Rag2-knockout mice, which cannot produce mature T- and B-cells, and were unable to promote the development of colitis, in contrast to wild-type T-cells." (PMID 37509095, 2023). "While there also appears to be a dysfunction in the naïve T cells similar to that reported in the Mettl3-deficient naïve T cells, the Treg dysfunction is predominant because the mice developed a proinflammatory colitis phenotype that could be reversed by adoptively transferring WT Treg cells." (PMID 32634481, 2020). "This will contribute to a more complete understanding of the mechanisms of action of UAF1 and METTL3 in colitis." (PMID 39966502, 2025). "The depletion of Mettl3 dramatically restricts intestinal development and goblet cell differentiation and induces spontaneous colitis in mice." (PMID 39762134, 2025). "Based on these previous and current findings, the up-regulation of METTL3 in colon inflammation suggests potential involvement of m6A modification in the progression of colon inflammation." (PMID 38725850, 2024). "m6A has been reported its potential connections with IBD, METTL3 and METTL14 deficiency in immune cell induce colitis; m6A eraser FTO protects IBD patients from adverse reactions after thiopurine treatment." (PMID 35127705, 2021). "Several investigations have confirmed that knocking down METTL3 could improve the symptoms of mouse model colitis, in which autophagy/mitophagy may be frequently stimulated in cells of the colitis." (PMID 40218916, 2025). "This will not only help to more fully assess the role of UAF1 and METTL3 in the pathogenesis of colitis, but could also provide key clinical evidence for the development of new treatment strategies." (PMID 39966502, 2025). "Additionally, In vivo experiments verified that knocking down circPRKAR1B and methyltransferase‐like 3 (METTL3) ameliorated experimental colitis in mice with IL‐10‐knockout (IL‐10‐KO)." (PMID 37679886, 2023). "Knockout of Mettl3 in mouse T cells caused failure of naïve T cells to proliferate and differentiate; in a lymphopaenic adoptive transfer model, most naïve Mettl3-deficient T cells remained naïve, and no signs of colitis were present." (PMID 29061143, 2017). "In a study in which palmatine (PAL) improved experimental colitis in rats, PAL significantly increased the expression levels of METTL3, METTL14, and ZO-1 and repaired intestinal barrier dysfunction." (PMID 40829428, 2025). "Given the important role of the gut microbiota in the pathogenesis of colitis, the potential effects of UAF1 inhibition or METTL3 activity on microbial composition and function are also of concern." (PMID 39966502, 2025). "Collectively, these data suggest that Mettl3 depletion in Lgr5+ stem cells inhibits the self-renewal and differentiation and promotes DSS-induced colitis." (PMID 39762134, 2025).
colitis (continued). "In conclusion, the present study indicated that the m6A-forming enzyme METTL3 controls UAF1 stabilization, promoting inflammation in the mouse model of colitis by enhancing NLRP3." (PMID 39966502, 2025). "Animal studies have confirmed that overexpression of the m6A methyltransferase, METTL3, aggravates LPS-induced inflammation of IECs and DSS-induced colitis in mice." (PMID 39706833, 2024). "The findings suggested that METTL3, as an m6A-forming enzyme, could regulate UAF1 mRNA, promoting inflammation in colitis through NLRP3 induction." (PMID 39966502, 2025). "A CD4-Cre loxP-flanked-METTL3 (METTL3fl/fl) mouse model exhibited more circulating naive T lymphocytes and less abundant activated CD4+ T cells, thus exerting a preventive role in the evolving colitis." (PMID 35127705, 2021). "METTL3 and METTL4-deficient T helper cells do not induce colitis as they cannot differentiate into pathogenic effector T cells." (PMID 35127705, 2021). "In CD4+ T-cell-specific Mettl3 KO mice, the proportion of naïve cells was higher, while the proportion of activating CD4+ T cells was lower than that in WT mice, and Mettl3 KO mice developed spontaneous colitis, indicating that m6A helped to keep naïve cells quiescent." (PMID 36225914, 2022). "Furthermore, T cells lacking METTL3 could not undergo homeostatic expansion in a mouse model of adoptive transfer‐induced lymphopaenia, ultimately preventing colitis." (PMID 37679886, 2023).
endometriosis (15 papers, 2021 to 2025). The growth of functional endometrial tissue in anatomic sites outside the uterine body. "The researchers also showed that the reduction in m6A in endometriosis was caused by METTL3 downregulation." (PMID 36894952, 2023). "We constructed a diagnostic m6A signature of endometriosis and found that METTL3 and YTHDF2 might be the key m6A targets of EM through experiments." (PMID 36675186, 2023). "METTL3 significantly inhibits the endometriosis progression by increasing cell senescence through the SIRT1/FOXO3 signaling pathway." (PMID 40867549, 2025). "In cases of endometriosis, METTL3 expression and m6A levels in ectopic and eutopic endometrial tissues were significantly lower than those in the normal control group." (PMID 40867549, 2025). "Another study reported that METTL3-mediated m6A methylation epigenetically regulates the progression of endometriosis through the METTL3-YTHDF2-SIRT1/FOXO3a axis." (PMID 40000966, 2025). "METTL3 knockdown enhances cell invasion and migration in a METTL3/m6A/miR126 axis-dependent manner, thereby promoting the development of endometriosis." (PMID 41194259, 2025). "Analysis of GEO datasets reveal a significant downregulation of METTL3 expression in the uterus of infertile women with endometriosis or recurrent implantation failure." (PMID 37270544, 2023). "The present study explores METTL3-mediated m6A modification and the mechanisms involved in endometriosis." (PMID 37353804, 2023). "Still, only a limited mechanism of METTL3–m6A–YTHDF2 in endometriosis was studied in this paper, and thus subsequent experiments are needed to verify our research results." (PMID 36675186, 2023). "Our findings demonstrate that METTL3-mediated m6A methylation epigenetically regulates the ectopic implantation of ESCs, resulting in the progression of endometriosis." (PMID 37353804, 2023). "Through extensive public database mining, we observed in this study that the mRNA of METTL3 was decreased in endometrium from infertile women with endometriosis or RIF." (PMID 37270544, 2023). "Endometriosis patients have lower levels of m6A in the endometrium than normal endometrium, and this reduction is due to lower levels of METTL3." (PMID 35813486, 2022). "Many studies have shown that the pathogenesis of endometriosis may be related to m6A, and some of these regulators, including METTL3, YTHDF2, YTHDF3, HNRNPC, HNRNPA2B1, and FTO, are significantly dysregulated in the ectopic endometrium." (PMID 40356909, 2025). "On the other hand, METTL3 overexpression has the opposite effects, which may provide ideas for further studies of endometriosis." (PMID 40356909, 2025). "Zhang reported that m6A alterations may be key factors in the progression of endometriosis, particularly the significant downregulation of METTL3 and YTHDF2 expression." (PMID 40000966, 2025). "For example, the first investigation into how m6A regulators function in endometriosis indicated that m6A regulators in endometriosis, such as METTL3, YTHDF2, YTHDF3, HNRNPC, HNRNPA2B1, and FTO, are significantly dysregulated compared with normal endometrial tissue." (PMID 36894952, 2023). "Our study reveals that METTL3 expression is significantly decreased in endometrium from infertile women with endometriosis or recurrent implantation failure, suggesting that m6A modifications might be involved in the pathogenesis of infertility." (PMID 37270544, 2023). "Recent studies have proved that m6A methylation transferase methyltransferase like 3 (METTL3) might play a key role in the development of endometriosis, while the other two m6A regulators, FTO and IGF2BP2, have also been reported to participate." (PMID 36672827, 2022). "Moreover, METTL3 expression in endometriosis was reduced in the ectopic vs. eutopic endometrium while FTO expression was elevated." (PMID 34906165, 2021).